FOXP1 (forkhead box P1)
Diseases named in the same sentence as FOXP1 in open-access papers (continued):
Sharing a sentence is not in itself a finding about the gene and the disease.
tumor (continued). "Interestingly, FOXP1 transcription factor, located on chromosome 3(p13), can function as a tumor suppressor gene." (PMID 26768750, 2016). "However, TGF-β is among the suppressive factors in the tumor environment that increases expression of the transcription factor Foxp1 in TIL." (PMID 26393659, 2015). "FOXP1 expression levels are inversely correlated with proliferative activity and tumorigenicity in vitro, supporting its role as a transcriptional regulator with critical tumor suppressor functions in solid tumor biology." (PMID 25406647, 2014). "We also find important tumor suppressors: FOXP1 (Forkhead box P1), a transcription factor that is believed to act as a tumor suppressor as it is lost in several tumor types, carries 15 predicted target sites from the most upregulated miR-seeds, and a significant downregulation is detected." (PMID 19557174, 2009). "We then analyzed whether the upregulation of FOXP1 leads to increased proliferation of tumor cells." (PMID 40169859, 2025). "Interestingly, FOXP1 plays a role in promoting or inhibiting cancer in different tumours." (PMID 38652109, 2024). "Consequently, FOXP1 may function as a novel biological target for tumour therapy as well as a biomarker for predicting the prognosis of oesophageal squamous cell carcinoma." (PMID 38652109, 2024). "Therefore, we concluded that FOXP1 served as a tumor suppressor in PC progression." (PMID 36952469, 2023). "However, our study found that FOXP1 acted as a tumor suppressor in PC progression." (PMID 36952469, 2023). "On the basis of our findings that FoxP1 is sufficient to repress muscle‐specific gene expression and induce muscle wasting, we next sought to determine whether the up‐regulation of endogenous FoxP1 mediates muscle wasting in response to tumour burden." (PMID 33527776, 2021). "Indeed, several downstream targets of MEF2 involved in muscle structure and function were among the top FoxP1 target genes repressed in response to tumour burden, including Casq1, Casq2, Lmod3, Ky, and Mef2c —suggesting that FoxP1 up‐regulation disrupts MEF2 transcriptional activity." (PMID 33527776, 2021). "Notably, as 83% of the identified FOXP1 fusion genes in our cohort have been detected in TNBC patients, we conclude that FOXP1 may act as a tumor suppressor independently of ER expression." (PMID 31745703, 2020). "Moreover, Foxp1 is overexpressed in tumour-infiltrating lymphocytes." (PMID 31594465, 2019). "Hence, the role of FOXP1 in tumour progression is uncertain." (PMID 29934982, 2018). "Additionally, solid tumor patients with decreased FOXP1 protein expression in tumor tissues may indicate sensitivity to chemotherapy." (PMID 27457567, 2016). "However, as more original studies regarding the association between the overexpression of FOXP1 and survival outcomes in tumor patients will be conducted, a systematic study on the prognostic value of overexpressed FOXP1 protein in tumor patients can also be performed in the future." (PMID 27457567, 2016). "Thus, the function of FOXP1 in tumor development and progression is inconsistent." (PMID 27457567, 2016). "For example, because our lab has recently demonstrated that FoxP1 is fundamental for TGFβ immune-mediated suppression in activated T cells, it would be interesting to determine whether targeting FoxP1 in ex vivo expanded γ T cells would enhance their anti-tumor effector functions." (PMID 25897427, 2015). "Of those, eight (HOXA3, HOXA5, ATP10A, SOX2, MIR922, ADAMTSL1, KHDRBS2, and LITD1) were hypermethylated in at least one LS tumor group like here in FAP normal, whereas NEDD4L, and FOXP1 were hypermethylated in LS carcinomas and here in LS normal." (PMID 40753397, 2025). "The transcription factor Foxp1 plays a regulatory role in the HIF-1α-HK2 pathway, which can improve the high glycolysis of tumor ECs and limit tumor angiogenesis, thereby effectively slowing down tumor growth." (PMID 40141029, 2025).
tumor (continued). "Forkhead box P1 (FOXP1) is an important member of the FOX family, which widely expresses in human normal and tumour tissues to varying degrees." (PMID 38652109, 2024). "In contrast, luminal A/B tumor cells and LM cells showed high accessibility for the ER ESR1, as well as forkhead proteins, including FOXA2 and FOXP1, GATA3 and other GATA-box TFs, and HNF1A." (PMID 39478117, 2024). "For example, it has been observed that FOXP1 inhibits the expression of the interleukin-7 (IL-7) receptor α chain (IL-7Rα) in CD8 + T cells and phosphorylates MEK and ERK to exert an anti-tumor effect." (PMID 38279090, 2024). "Moreover, through RNA sequencing analysis in tumor CD8+ T cells, we found that genes associated with effector functions, such as Sox6, Ccnd1, CD81 and Trim14, were upregulated, while genes associated with immune inhibition, such as Tox, Jun-b, Btla, Batf and Foxp1 were downregulated 25-27." (PMID 38994031, 2024). "Altogether, these findings demonstrate that FOXP1 overexpression inhibits ICC progression via the promotion of apoptosis, suggesting a tumor suppressor role for FOXP1." (PMID 38279090, 2024). "EBV-miR-BART11 and EBV-miR-BART17-3p inhibit FOXP1 and PBRM1, respectively, and enhance the transcription of PD-L1, thus promoting tumor immune escape." (PMID 38428879, 2024). "We further validated the inhibitory effect of FOXP1 on the proliferation of oesophageal squamous cell carcinoma cells through CCK‐8, colony formation and subcutaneous tumour formation assays." (PMID 38652109, 2024). "We found that FOXA1 and FOXM1 were significantly positively correlated with tumor purity in patients with BRCA, while FOXC2, FOXO3, FOXP1, and FOXQ1 were significantly negatively correlated with tumor purity in patients with BRCA." (PMID 38608123, 2024). "We found that FOXM1, FOXP1, and FOXN3 were negatively correlated with OS and that FOXP1 and FOXN3 were positively correlated with histological grade and tumor size." (PMID 36622275, 2023). "Of note, FOXP1-bound IRF1 promoter was found by luciferase and ChIP assays, suggesting a possibly of elevating the expression level of IRF1 that inhibited tumor cell growth and invasion." (PMID 36952469, 2023). "Therefore, consistent with the role of the NAT10/ac4C/FOXP1 axis in facilitating the upregulation of immune checkpoint genes and subsequent immune evasion, inhibition of this axis resulted in PD‐L1 blockade‐induced tumor regression that correspondingly inhibited CCa progression." (PMID 37818745, 2023). "FOXP1 establishes interactions with the PBAF subtype to which PBRM1 belongs, binds to the PD-L1 enhancer, and promotes PD-L1 transcription, resulting in tumor immune escape." (PMID 35165282, 2022). "FOXP1 is a member of the FOXP subfamily, which is expressed in various tissues of the body and demonstrates a tumor suppressor effect in a variety of solid tumors." (PMID 35165282, 2022). "TISIBD was employed to analyze the relationship between FOXP1, FOXP2, FOXP3, and FOXP4 and tumor-infiltrating immune cells in 28 kinds of tumor." (PMID 36203616, 2022). "Forkhead Box P1 (FOXP1) belongs to the forkhead box transcription factor family, and has known to have dual roles as a tumor suppressor gene and as an oncogene in multiple cancer types." (PMID 32552834, 2020). "FOXP1 and FOXP2 fall under the FOXP sub-family (also comprising FOXP3 and FOXP4) which has functions in oncogenic and tumor suppressive pathways." (PMID 32066696, 2020). "Since Foxp1 expression is highest in LOVO and lowest in SW620 in tumor cells, we overexpressed Foxp1 in SW620 cells and knocked down Foxp1 in LOVO cells to observe the effect of Foxp1 on circFoxp1 expression." (PMID 32951006, 2020).
tumor (continued). "NK_c3 and NK_c5 were mainly derived from non-tumor liver tissues (23.57% and 5.97%, respectively) and characterized by high expression of transcription factors such as FOS, FOSB, FOXP1, and ATF4, and two genes involved in the NF-κB pathway, NFKBIA and NFKBIZ." (PMID 33298893, 2020). "In contrast, miR-34a has been identified as a tumor suppressor miRNA by repressing several target genes, such as cyclin-dependent kinase 4 (CDK4), CDK6, BCL2, MET, Notch, c-MYC, AXL and FOXP1." (PMID 31472685, 2019). "Collectively, these observations indicate FOXP1 is oncogenic, and that epigenetic regulation of the FOXP1 promoter is one mechanism by which PRMT5 drives BCSC function, promoting tumour initiation and drug resistance." (PMID 29876520, 2018). "More recently, it was demonstrated that, in tumor microenvironment, TGF-β-mediated upregulation of Foxp1 primarily in CD8+ T cells renders them unresponsive toward immunity against tumors." (PMID 30367168, 2018). "Taken together, these results suggest that CD8+ effector subgroups differ in Foxp1 expression and apoptotic response to TGF-β exposure, and that NTeff cells maintain resistance to inhibitory factors induced from the tumor microenvironment." (PMID 27306834, 2016). "Systemic miR-34a administration downregulated FOXP1 expression and induced apoptosis in a DLBCL xenograft mouse model, leading to significant tumor suppressing effect." (PMID 27172795, 2016). "NTeff cells appeared to have lower expression of Foxp1 and were refractory to apoptosis upon TGF-β conditioning, implying better survival potential and resistance to tumor-induced immune suppression." (PMID 27306834, 2016). "Among those putative target candidates, five potential tumor suppressors, including CCNG2, FOXP1, NRG1, LRIG1, and TNFSF10, were shown to have a direct binding site with miR-130b-5p." (PMID 25888956, 2015). "Furthermore, we confirmed that PDAC cells utilized LMO7 to decrease Foxp1 protein levels in vivo, promoting the secretion of TGF-β/CCL5 and Treg cell infiltration within the tumor tissue." (PMID 39143228, 2025). "An analysis of the correlation between UHRF1 expression and that of its target genes in scT‐LBLs demonstrated that the tumour suppressor genes FOXP1, PIK3R1 and KLF6 exhibited a significant negative correlation with UHRF1 expression." (PMID 40579780, 2025). "Similarly, tumor tissues exhibited higher FBXO44 and Cyclin E2 protein expression and lower FOXP1 protein expression compared to adjacent normal tissues." (PMID 41051444, 2025). "FOXP1 expression demonstrated a negative correlation with the infiltration of tumor-promoting immune cells, such as macrophages, dendritic cells, and myeloid-derived suppressor cells (MDSCs)." (PMID 40672953, 2025). "Also, silencing FOXP1 and inhibiting ABCG2 in orthotopic mouse models led to significant reductions in tumor sizes, highlighting the clinical potential of therapeutics against FOXP1." (PMID 40169859, 2025). "FOXP1 was also reported to act as a tumor suppressor and negatively regulate immune responses, including cytokine and chemokine expression, in breast cancer." (PMID 38279090, 2024). "Super‐enhancers exert a major role in the progression of various tumor types including PCa and also contribute to resistance mechanisms involving SE‐binding factors such as BRD4 or FOXP1." (PMID 32333502, 2020). "In both tumour cell lines, LINC01614 knockdown significantly inhibited FOXP1 expression (P < 0.01)." (PMID 29934982, 2018). "The same number of A2780 cells with or without FOXP1 knockdown were injected into each side of nude mice, and tumor growth in mice was observed for 35 days." (PMID 26654944, 2016). "It has been hypothesized that the role of FOXP1 as oncogene is due to expression of short FOXP1 isoforms, while the full length FOXP1 (FOXP1FL) acts as tumor suppressor." (PMID 24416450, 2014). "EIF4E3 falls in between FOXP1 and RYBP, and is itself a purported tumor suppressor." (PMID 25155515, 2014).
tumor (continued). "Of course, other indirect target genes, such as the forkhead box P1(FOXP1) gene, belongs to subfamily P of the forkhead box (FOX) transcription factor family, have been reported to act as a candidate tumor suppressor gene localized to the chromosome 3p14, 1 region." (PMID 24069310, 2013). "Indeed, FOXP1 overexpression decreases NF-κB p65 protein expression, while EBV-miR-BART11 overexpression or FOXP1 knockdown increases NF-κB p65 expression, indicating the role of NF-κB in the crosstalk between NPC cell and TAMs in response to inflammation and tumor development." (PMID 38397187, 2024). "NAT10 upregulates the transcription factor Forkhead box P1 (FOXP1) in CC to form the NAT10/ac4C/FOXP1 axis, which accelerates glycolytic metabolism, increases lactate production, and promotes immunosuppression in the tumor microenvironment by reprogramming glycolysis." (PMID 39640362, 2024). "However, upregulation of GINS1 rescued the tumor volumes and weights suppressed by FOXP1- silencing in the SU-DHL2-shFOXP1+oeGINS1 groups, indicating that GINS1 overexpression reversed the growth inhibition induced by FOXP1 knockdown." (PMID 37576391, 2023). "Consistent with the in vivo results, the results in this model confirmed that overexpression of FOXP1 can attenuate the suppressive effect of NAT10 knockdown on tumor growth in vivo, further emphasizing the crucial role of ac4C modification catalyzed by NAT10 in CCa tumor development." (PMID 37818745, 2023). "Cluster 1 was characterized by upregulation of tumor-suppressing genes: HNF1B, CCNDBP1, PATJ, EPB41L3, MARVELD2, PTEN in conjunction with cell-cycle genes – GSPT1, GPR19, EAPP, KIT, CDKL1, and stem cell markers – RBBP5, NANOG, NCSTN, ERG, including quiescent stem cell markers—FOXP1, SMARCA2." (PMID 36348001, 2022). "Previous studies from our laboratory, and others, have established the importance of the FoxO transcription factors in promoting tumour‐induced muscle wasting, and our previous work identified FoxP1—whose role in skeletal muscle has not been studied to this date—as a FoxO‐dependent gene." (PMID 33527776, 2021). "Thus like many transcription factors including FOXP1, FOXP2 may function as either an oncogene or tumor suppressor depending on cellular context." (PMID 27224915, 2016). "We also detected somewhat puzzling hypermethylation and silencing of genes that would be predicted to be oncogenes, rather than tumor suppressors, such as SF3B1, LCK, FOXP1, and FYN." (PMID 39189258, 2024). "We also detected somewhat puzzling hypermethylation and silencing of genes that would be predicted to be oncogenes, rather than tumor suppressors, such as SF3B1, LCK, FOXP1, FYN50,51." (PMID 38464090, 2024). "Correlation analysis showed that there was a negative expression correlation between FOXP1 and CLRN1-AS1 in tumor samples." (PMID 31235696, 2019). "Unlike virally-exhausted CD8 T cells, Foxp1 expression is overexpressed to varying degrees by TIL from all queried murine and human tumor environments." (PMID 26393659, 2015). "FOXP1 works as a negative regulator of tumor-specific CD4+ T helper 7 (Th7) cells for cancer immunotherapy, since mature naïve CD4+ T cells proliferate to exert antitumor effect programmed by IL-7 only in the absence of FOXP1." (PMID 31815635, 2019).
cancer (123 papers, 2010 to 2026). A tumor composed of atypical neoplastic, often pleomorphic cells that invade other tissues. "FoxP1 is a multidomain transcription factor implicated in development, immunity, and cancer, widely proposed to function as a dimer." (PMID 42282810, 2026). "We previously found that forkhead box P1 (FoxP1) upregulation in skeletal muscle causes muscle wasting and is required for muscle wasting in response to cancer." (PMID 40349340, 2025). "A FOXP1 deficiency is intimately related with a series of physiological disorders including developmental retardation and cancer, the pathogenesis of which correlate with dysregulation of the replication stress response." (PMID 39623140, 2025). "Taken together, the data indicated that EBV-miR-BART11 promoted PD-L1 expression by targeting and inhibiting FOXP1 expression in EBV-associated cancers." (PMID 35165282, 2022). "FOXP1 is ubiquitously expressed in the human body and is implicated in both physiological and pathological processes including cancer." (PMID 36268015, 2022). "Alterations in FoxP1 expression have also been associated with poor cancer‐survival prognosis, atherosclerosis, Huntington disease, heart failure, and cardiomyocyte hypertrophy." (PMID 33527776, 2021). "We further show that these findings are relevant to muscle wasting associated with cancer, as FoxP1 expression was elevated in multiple mouse models of cancer cachexia, and its knockdown attenuated cancer‐associated muscle fibre atrophy." (PMID 33527776, 2021). "Strong FAM13C expression was significantly linked to deletions of PTEN and 3p13 (FOXP1) if all cancers were jointly analyzed (p < 0.0001 each)." (PMID 28415558, 2017). "Combined loss of Foxp1-Shq1 and Pten resulted in significant acceleration of cancer development compared to Pten loss alone in mice." (PMID 29057879, 2017). "In conclusion, we revealed EBV-miR-BART11 plays an important role in the inflammatory microenvironment and inflammation-induced carcinogenesis in EBV-associated cancers through the direct inhibition of FOXP1 and NF-κB activation." (PMID 27167345, 2016). "The pathogenic mutations identified in patients with FOXP1 syndrome mainly locate in its forkhead domain, and this domain also contains multiple mutations in a broad spectrum of cancers as indicated in the TCGA database." (PMID 39623140, 2025). "Here, by conducting FoxP1 gain- and loss-of-function studies, we identify skeletal-muscle FoxP1 as a negative regulator of the skeletal-muscle clock that plays a key role in disrupting circadian patterns of gene expression in response to cancer." (PMID 40349340, 2025). "In this regard, we show that muscle-specific deletion of FoxP1 prevents the cancer-induced loss of rhythmic expression in 104 genes, 37 of which are direct FoxP1 targets and include genes related to carbohydrate metabolism, lipid metabolism, and mitochondrial regulation." (PMID 40349340, 2025). "They reveal cancer/disease-specific functions of FoxP1 in the disruption and reprograming of the skeletal-muscle circadian transcriptome, which may contribute to cancer-induced muscle loss." (PMID 40349340, 2025). "The others mapped to areas associated with cancer including FOXP1 (rs1288980) and ZEB1 (rs7349)." (PMID 38493193, 2024). "Some ASC-related genes, such as FOXP1 and copy number variation, are known to suppress tumors or cancer if they are intact, requiring further examination to explore how such a genetic background interacts with steroid excess contributing to cancer risk." (PMID 38752176, 2024). "On the basis of our findings that FoxP1 is both sufficient and required for cancer‐associated muscle wasting, we sought to determine whether our findings are relevant to skeletal muscle wasting in human cancer patients." (PMID 33527776, 2021).